TNF (tumor necrosis factor)
Diseases named in the same sentence as TNF in open-access papers (continued):
Sharing a sentence is not in itself a finding about the gene and the disease.
psoriatic arthritis (continued). "The authors propose that the sarcoidosis-like reaction observed in the patient was a consequence of the anti-TNF agent adalimumab used to treat the patient’s psoriatic arthritis." (PMID 39881908, 2024). "Tumor necrosis factor inhibitors (TNFi) are frequently chosen as the first biologic for patients with psoriatic arthritis (PsA)." (PMID 38773563, 2024). "Several studies have demonstrated the efficacy of inhibitors of IL-6, IL-17, and TNF-α in the management of chronic plaque psoriasis and psoriatic arthritis." (PMID 39411067, 2024). "Considering the importance of DISR as a secondary effect of the administration of anti-TNF agents, we present the case of a 33-year-old woman with psoriatic arthritis treated with adalimumab, consistent with DISR." (PMID 39881908, 2024). "They showed remarkable efficacy in suppressing the development of psoriatic arthritis, even in the presence of persistent high levels of soluble TNFα." (PMID 38672485, 2024). "In conclusion, the case presented underscores the importance of vigilance regarding potential adverse effects of TNF-α antagonist therapy including also certolizumab, in patients with inflammatory conditions such as psoriatic arthritis." (PMID 39180528, 2024). "We describe the case of a patient, who was under long-term treatment with a tumor necrosis factor inhibitor (TNFi), for psoriatic arthritis (PsA) and developed an inflammatory mass in the spleen, accompanied by systemic manifestations." (PMID 39651014, 2024). "These transgenic mice develop severe psoriatic arthritis upon receiving doxycycline administered through water, as a result of the high expression of the human cytokine TNFα in both the bloodstream and the skin." (PMID 38672485, 2024). "In conclusion, the intricate interplay between managing psoriatic arthritis with anti-TNFα therapy and averting bacterial infections poses a significant dilemma." (PMID 38883009, 2024). "The treatment landscape for psoriatic arthritis (PsA) has evolved significantly with the introduction of biologic therapies, such as adalimumab, which effectively inhibits tumor necrosis factor-alpha (TNF-α) activity." (PMID 38883009, 2024). "Data on treatment switching directly from tumor necrosis factor inhibitors to tofacitinib in psoriatic arthritis (PsA) are limited." (PMID 39702318, 2024). "In this case, a patient diagnosed with psoriatic arthritis, who was under adalimumab treatment, has been prescribed tenofovir (Vemlidy®) at a dosage of 300 mg once daily since the initiation of anti-TNFα biologics." (PMID 38883009, 2024). "One patient was affected by psoriatic arthritis in monotherapy with an anti-TNF monoclonal antibody (golimumab)." (PMID 36851094, 2023). "For instance, male patients exhibited a better baseline profile than female patients in a large cohort of psoriatic arthritis patients who started TNF inhibitor as their first medication." (PMID 37954855, 2023). "While many algorithms have been developed to guide clinicians on how to treat psoriatic arthritis and its different subtypes, this review focused on golimumab’s reported safety and efficacy profile compared with other commonly used TNF-a inhibitors." (PMID 37511975, 2023). "In patients with psoriatic arthritis, the effect of anti-TNF-α therapy on TC, TG, and LDL-C was significantly reduced after 36 months of treatment." (PMID 36771367, 2023). "In the psoriatic arthritis group, 33 patients were included, who were treated with TNF-alpha inhibitors as follows: Etanercept (48.5%), Infliximab (24.2%) and Adalimumab (27.3%)." (PMID 37370974, 2023). "In vitro -induced IL-17A+ CD8+ T-cells increase the production of proinflammatory cytokines from psoriatic arthritis synovial fibroblasts; this was reduced by IL-17A and TNFα blockade." (PMID 37367825, 2023).
psoriatic arthritis (continued). "Golimumab should be used in patients with psoriatic polyarticular idiopathic juvenile arthritis and psoriatic arthritis, with treatment responses expected to mirror the efficacy demonstrated by older TNF-a inhibitor therapies." (PMID 37511975, 2023). "Although the efficiency of ustekinumab in treating psoriatic arthritis is lower and slower compared with anti-TNF-α agents, ustekinumab was able to contain joint and skin disease for a long time." (PMID 37764964, 2023). "The current literature indicates an elevated level of tumor necrosis factor is present in the epidermis of patients with psoriatic arthritis when compared with the general population." (PMID 37511975, 2023). "In the pathophysiology of psoriatic arthritis, the central role of TNF-α and IL-17 had been highlighted." (PMID 37627974, 2023). "TNF-alpha inhibitors evidently reduced the total hospital stay period for patients with psoriatic arthritis." (PMID 36185325, 2022). "About 57 out of 107 targeted proteins were found to be predictive to anti-TNF treatment response with AUC of 0.76 in psoriatic arthritis." (PMID 35788746, 2022). "On the contrary, a decreased LOS was found in psoriatic arthritis patients treated with TNF-alpha inhibitors (Adjusted coefficient: -2.21, 95%CI: -4.37 to -0.05)." (PMID 36185325, 2022). "Adalimumab is a fully humanized monoclonal IgG1 antibody and tumor necrosis factor α (TNFα) antagonist used in several indications, including moderate-to-severe plaque psoriasis and psoriatic arthritis." (PMID 36004912, 2022). "As trials have demonstrated its efficacy in psoriatic arthritis, and more importantly in those previously exposed to TNF inhibitors, it was also approved for active psoriatic arthritis, alone or in combination with methotrexate." (PMID 35860015, 2022). "Interleukin (IL)-17 and tumor necrosis factor-alpha (TNF)-α are key players in psoriatic arthritis (PsA) pathogenesis." (PMID 35203534, 2022). "The pathogenesis of psoriatic arthritis is related to the innate and adaptive immune response involving different proinflammatory cytokine, including TNF, IL-1β, IL-6, IL-22, IL-23, IL-17A, and IL-18." (PMID 36297574, 2022). "Psoriasis and psoriatic arthritis are characterized by tissue infiltration by activated T cells thereby resulting in an increased TNFα, IL 17 and IL 23 production." (PMID 34010320, 2021). "In psoriatic arthritis, for example, its expression is stimulated by IL-17, and thus TNF-α is located “downstream” of it." (PMID 34829740, 2021). "For example, TNFα-, IL-6R- and IL-1β-neutralizing bDMARDs work in RA, whereas IL-17A and IL-12/23-neutralizing bDMARDs are very efficient in psoriatic arthritis or spondyloarthritis." (PMID 34680530, 2021). "There are currently four FDA-approved TNF-α inhibitors: etanercept, infliximab, adalimumab, and certolizumab (and one additional one, golimumab, which is approved for psoriatic arthritis)." (PMID 34884596, 2021). "A meta-analysis of five studies including 49,795 patients with plaque psoriasis or psoriatic arthritis also verified the efficacy of anti–TNF-α therapy in decreasing the incidence of cardiovascular events." (PMID 34803716, 2021). "In a number of guidelines, TNF-α inhibitors are considered to be the drugs of choice for plaque psoriasis and psoriatic arthritis." (PMID 33613635, 2021). "The systemic bone loss resulting in a reduced bone mineral density (BMD) and the role of TNFα antibodies in this process are a matter of debate in psoriatic arthritis." (PMID 34010320, 2021). "For example, a phase III randomized clinical trial of apremilast found a significant decrease in TNF-α, IL-6, and IL-8 levels in psoriatic arthritis patients after 24 weeks of BID dosing." (PMID 33052879, 2020). "Tumour necrosis factor inhibiting agents (TNF-inhibitors, TNFi) are effective and safe in the treatment of spondyloarthritis (SpA) such as psoriatic arthritis (PsA) and axial spondyloarthritis (axSpA)." (PMID 31941544, 2020).
psoriatic arthritis (continued). "In recent years, it has been demonstrated that TNF-α represents one crucial element in the development of psoriatic arthritis, and both direct and receptor TNF-α inhibitors are currently utilized as well-tolerated pharmacological treatments." (PMID 32971792, 2020). "Adalimumab is an anti-tumor necrosis factor (TNF) alpha monoclonal antibody used to treat psoriatic arthritis." (PMID 32150046, 2020). "TNFα inhibition using monoclonal antibodies has been effective for treating both rheumatoid and psoriatic arthritis." (PMID 31470613, 2019). "Persistence in the use of anti-TNF and conventional synthetic disease-modifying antirheumatic drug medications in individuals with psoriatic arthritis." (PMID 30820348, 2019). "b.i.d. = twice daily; csDMARD = conventional synthetic disease-modifying antirheumatic drug; IR = inadequate responder; PK = pharmacokinetics; PsA = psoriatic arthritis; Q2W = every 2 weeks; TNFi = tumor necrosis factor inhibitor." (PMID 31319908, 2019). "In a small case series of hemophilia A patients with overlapping RA or psoriatic arthritis, systemic anti-TNF-α therapy with adalimumab proved to be useful not only in controlling synovitis and inducing disease remission but also in reducing joint bleeding." (PMID 31261789, 2019). "Our presumed diagnosis was bilateral sacroililitis secondary to psoriatic arthritis, and the patient was started on adalimumab, a tumor necrosis factor alpha blocker (TNF alpha) therapy." (PMID 29678187, 2018). "Treatment options for psoriatic arthritis (PsA) increased significantly in the last decade with leflunomide and tumor necrosis factor (TNF) inhibitors (TNFi) becoming part of our standard therapeutic arsenal." (PMID 29017591, 2017). "Tumor necrosis factor (TNF)–alpha is a potent proinflammatory cytokine involved in the pathogenesis of many inflammatory and autoimmune conditions, including psoriatic arthritis." (PMID 28717771, 2017). "In psoriatic arthritis patients, anti TNF-α monoclonal antibodies have been developed for neutralization of TNF and etanercept for LT-α41." (PMID 28642550, 2017). "TNF-α was also considered as a major candidate gene in psoriatic arthritis (PsA) as TNF-α was present in high levels in serum, synovial fluid, and synovial membrane in patients with PsA." (PMID 27652081, 2016). "Real-world data regarding anti-tumor necrosis factor alpha (anti-TNFα) biologic therapy use in psoriatic arthritis (PsA) are limited; therefore, we described treatment patterns and costs of anti-TNFα therapy in PsA patients in the United States." (PMID 27301458, 2016). "We similarly identified immune-mediated and inflammatory markers of injury in a psoriatic arthritis patient who developed an amyotrophic lateral sclerosis (ALS)-plus syndrome after tumor necrosis factor (TNF)-inhibitor therapy." (PMID 26252269, 2015). "Such an example is epitomized in Patient 8, who was diagnosed with the neurodegenerative disorder of ALS in the context of being treated with TNF-inhibitor therapy for psoriatic arthritis." (PMID 26252269, 2015). "American College of Rheumatology (ACR) response rates for psoriatic arthritis are somewhat higher for TNF antagonists than for ustekinumab." (PMID 26633680, 2015). "Patient 8 had psoriatic arthritis and was treated with the TNF-inhibitor infliximab, and was diagnosed with ALS after 1 year of treatment." (PMID 26252269, 2015). "For example, TNF antagonists are regarded as biologicals of first choice in patients with psoriatic arthritis." (PMID 26633680, 2015). "In patients with psoriatic arthritis, apremilast has been shown to reduce plasma levels of TNF- α, IL-6, and other pro-inflammatory cytokines and chemokines." (PMID 26370839, 2015). "PGRN antibodies entertained a proinflammatory environment in a subgroup of patients with psoriatic arthritis, and TNF-α-induced cytotoxicity assays demonstrated that the protective effects of PGRN were inhibited by serum containing PGRN antibodies." (PMID 24651300, 2014).
psoriatic arthritis (continued). "This notion is reinforced by the results of clinical trials based on the administration of anti-TNF-α therapy in patients with psoriatic arthritis." (PMID 25136144, 2014). "Anti-TNFα agents (i.e., etanercept, adalimumab, and infliximab) have established efficacy in treating psoriatic arthritis and are therefore preferred in patients with concomitant psoriatic arthritis." (PMID 24605338, 2014). "We determined the expression of ILT4 and analysed the relationship with the expression of costimulatory proteins and tumor necrosis factor-α (TNF-α) production in monocytes from patients with psoriatic arthritis (PsA) starting anti-TNF treatment." (PMID 24676037, 2014). "This is a retrospective study in 321 patients with PsA, attending the Psoriatic Arthritis Clinic at the University Federico II of Naples, who had an inadequate response to DMARDs and started therapy with TNF-α blockers." (PMID 24554385, 2014). "It has been confirmed that tumor necrosis factor-alpha (TNFα), a macrophage-derived pro-inflammatory cytokine, plays an important role in the pathogenesis of psoriasis vulgaris and psoriatic arthritis (PsV&PsA)." (PMID 23717605, 2013). "Use of TIDI during the NICE appraisal of tumor necrosis factor-alpha inhibitors (in psoriatic arthritis) successfully demonstrated its ability to facilitate critiques of the decision models by decision makers." (PMID 21839417, 2011). "This approach has been adopted by the authors in a NICE appraisal of the use of TNF-alpha inhibitors in treatment of psoriatic arthritis." (PMID 21839417, 2011). "Since remission is now possible in psoriatic arthritis (PsA) we wished to examine remission rates in PsA patients following anti tumour necrosis factor alpha (TNFα) therapy and to examine possible predictors of response." (PMID 20482783, 2010). "Therapeutic experience strongly supports the use of TNF antagonists as important modalities in the treatment of psoriatic arthritis and plaque psoriasis." (PMID 20606888, 2010). "A total of 566 patients with psoriatic arthritis were registered with the British Society for Rheumatology Biologics Register (first anti-TNF agent: etanercept, n = 316; infliximab, n = 162; and adalimumab, n = 88)." (PMID 19356232, 2009). "The development of anti-TNF therapies has dramatically improved the management of a range of autoimmune diseases, including psoriatic arthritis (PsA)." (PMID 19356232, 2009). "Psoriatic arthritis patients show high persistence rates with both initial and second anti-TNF therapies." (PMID 19356232, 2009). "The BE COMPLETE study, a multicenter, double-blind, placebo-controlled, randomized phase III trial, assesses the efficacy of bimekizumab in patients with active psoriatic arthritis who previously experienced inadequate responses or intolerance to anti-TNF therapy." (PMID 40076933, 2025). "TNF‐α antagonists represented by adalimumab, infliximab, and golimumab effectively inhibit proinflammatory signaling by blocking the interaction between TNF‐α and its receptors, significantly reducing joint destruction and skin inflammation in diseases such as RA, psoriatic arthritis, and IBD." (PMID 40529617, 2025). "Our previous research demonstrated the effectiveness of small spleen peptides (SSPs), a fraction of low molecular weight proteins, in inhibiting the progression of psoriatic arthritis, even in the presence of high levels of the proinflammatory cytokine TNFα in the bloodstream." (PMID 38773618, 2024). "Our previous research demonstrated the effectiveness of small spleen peptides (SSPs) in inhibiting psoriatic arthritis progression, even in the presence of the pro-inflammatory cytokine TNFα, by transforming dendritic cells (DCs) into tolerogenic cells and fostering regulatory Foxp3+ Treg cells." (PMID 38672485, 2024).
psoriatic arthritis (continued). "Both conventional and unconventional IL-17A+ CD8+ T-cells were able to induce pro-inflammatory IL-6 and IL-8 production by synovial fibroblasts from patients with psoriatic arthritis, which was reduced upon addition of anti-TNFα and anti-IL-17A neutralizing antibodies." (PMID 37367825, 2023). "The presence of larger psoriatic lesions may be implicated in the elevation of tumor necrosis factor-alpha (TNF-α) levels, which have been observed in the synovium, synovial lining, and skin lesions of individuals diagnosed with psoriatic arthritis." (PMID 37937010, 2023). "Thus, in psoriatic arthritis, anti TNF-α molecules, secukinumab, ixekizumab, guselkumab and risankizumab are indicated as a first-line treatment." (PMID 37374219, 2023). "The efficacy of anti-TNF agents, IL inhibitors, and abatacept may retard radiographic progression in psoriatic arthritis patients compared with placebo; however, this meta-analysis did not include guselkumab and lacked comparisons between different bDMARDs." (PMID 36297574, 2022). "Moreover, two recent meta-analysis showed a decreased incidence and mortality rate in psoriasis and psoriatic arthritis patients treated with anti-TNF therapy." (PMID 35160136, 2022). "In another study, 25 potential anti-TNF treatment predictive biomarkers based on significant differential expression between good and poor response were suggested out of 119 investigated proteins in psoriatic arthritis (n = 12)." (PMID 35788746, 2022). "In conclusion, anti-tumor necrosis factor agents (adalimumab, infliximab, and etanercept) may be preferred for treating psoriatic arthritis for their superiority in preventing radiographic progression." (PMID 36297574, 2022). "Anti-TNF-α therapy also has a favorable effect on the improvement of arterial stiffness, measured by the gold standard aortic pulse wave velocity (aPWV), in patients with psoriatic arthritis." (PMID 34803716, 2021). "Moreover, anti-TNF-α treatment in psoriatic arthritis patients reduced the number of peripheral osteoclast precursors." (PMID 34209821, 2021). "In addition, a case of successful treatment with secukinumab in recalcitrant psoriatic arthritis treated previously with 2 anti-TNF drugs was reported." (PMID 33150038, 2020). "Besides the established treatment of anti-TNF antibodies and ustekinumab for psoriatic arthritis, the newer treatment options of anti-IL-17 antibodies and apremilast are also effective for the treatment of PsA." (PMID 32121574, 2020). "Data from observational cohort studies suggest that TNF inhibitors for psoriatic arthritis are more effective in male than female patients, even when controlling for confounding variables, including comorbidities (e.g., chronic pulmonary disease) and lifestyle (e.g., smoking)." (PMID 32366281, 2020). "If TNF inhibitors are initiated in the early stages of psoriatic arthritis, this could potentially modulate disease and therefore allow us to discontinue the TNF inhibitor after achieving remission." (PMID 31521192, 2019). "While treatment with anti-Tumour Necrosis Factor-alpha (TNF-α) agents has proved to be effective in inflammatory arthropathies such as psoriatic arthritis, they have been employed in only a limited number of patients with autoimmune hepatitis, and their effectiveness is unclear." (PMID 27876037, 2016). "Although, mentioned earlier, adiponectin has been reported to be increased in RA patients, an increase in adiponectin levels after treatment with antirheumatic drugs in patients with RA or after anti-TNF therapy in psoriatic arthritis patients has also been described." (PMID 23781298, 2012). "TIDI has also been developed for an economic model (and associated evidence syntheses) commissioned by NICE assessing the cost-effectiveness of tumor necrosis factor alpha (TNF-alpha) inhibitors (etanercept, infliximab, and adalimumab) when used in treatment of psoriatic arthritis." (PMID 21839417, 2011).